MITF (melanocyte inducing transcription factor)
Diseases named in the same sentence as MITF in open-access papers (continued):
Sharing a sentence is not in itself a finding about the gene and the disease.
melanoma (continued). "However, in melanoma, an intrinsic balance between ZEB1 and ZEB2 seems to determine the cellular state by modulating the expression of the master regulator of melanocyte homeostasis, microphthalmia-associated transcription factor (MITF)." (PMID 32796736, 2020). "Interestingly, we show that acriflavine targets activating transcription factor 4 (ATF4) for proteasomal degradation while suppressing the expression of microphthalmia-associated transcription factor (MITF), a master regulator of melanocyte development and a melanoma oncogene." (PMID 33396270, 2020). "In addition, POU4F1 could increase the expression of MITF to retain the resistance of melanoma cells to BRAFi." (PMID 32532957, 2020). "Also, miR-211 revealed an important role in the regulation of POU3F2, the POU domain transcription factor that is better known as BRN2, a well-established MITF repressor, suggesting a further indirect influence of miR-211 in the development of melanoma metastasis." (PMID 32013263, 2020). "Thus, we further explored whether reversible acetylation of HINT1 could affect the interaction of HINT1 with MITF and then affect MITF-mediated oncogenic function in the A375 melanoma cell line." (PMID 32636443, 2020). "miR-182, a member of a miRNA cluster in chromosomal locus 7q31–34, is frequently described as amplified in A375 melanoma cell lines, acting as an oncomiR through the suppression of transcription factors forkhead box O3 (FOXO3) and microphthalmia-associated transcription factor (MITF)." (PMID 33348804, 2020). "The finding that the MiT-TFE factors are co-expressed in melanoma cells and tumors, together with recent evidence pointing to a role of MITF in the regulation of lysosomal and autophagy-related genes, similar to TFEB and TFE3, may suggest an overlap in function or cooperation between these factors." (PMID 32881934, 2020). "However, current literature on dermoscopic features of nevi and melanomas in these patients is still limited, and predisposition to non-melanoma cancers according to MITF germline status needs to be further investigated." (PMID 32054529, 2020). "In this study, we were able to prove that HuR not only holds a pro-tumorigenic function in melanoma but also bears the capacity to break oncogene-induced senescence in melanocytes via, amongst others, upregulation of MITF and thereby might be involved in the development of melanoma." (PMID 32455577, 2020). "Moreover, oncogenic MITF mediates melanoma progression in a “rheostat model”." (PMID 33293474, 2020). "To assess whether depletion of GTF2H1 recapitulates the senescence-like phenotype induced by knockdown of MITF, we utilized several independent siRNAs directed against GTF2H1, which caused a significant growth inhibition in vitro in a variety of melanoma cell lines." (PMID 30651597, 2019). "MITF or SOX10 have been extensively investigated and allowed a better comprehension of resistance to cancer therapies, underlying the importance of lineage specific signaling in our understanding of how melanoma still overcomes current treatments in the clinic." (PMID 31118886, 2019). "Moreover, FBXW7 was also found to regulate the oncogene MITF in melanoma." (PMID 30791487, 2019). "Similarly, MITF not just plays a crucial role in the differentiation state, but its loss leads to the metastatic phenotype of melanoma." (PMID 30900145, 2019).
melanoma (continued). "Single cell qPCR of melanoma patient primary tumors and distant metastases have revealed an MITF signature in intra- and intertumoral heterogeneity with coexpression of three distinct clusters of cells—MITF-high, MITF-low, and a subset expressing markers of both." (PMID 31547367, 2019). "MITF activates the expression of protein coding genes involved in differentiation and proliferation, DNA replication and repair, mitosis, oxidative phosphorylation and mitochondrial metabolism, and represses the transcription of genes involved in melanoma cell invasion and motility." (PMID 31881017, 2019). "Moreover, resveratrol was proven to be effective in inhibiting α-MSH-induced cancer stem cell-associated molecules, such as Wnt-1/β-catenin, c-Kit, MITF, and matrix metalloproteinase 9 (MMP-9), decreasing the cell viability, as well as suppressing the invasion of melanoma B16 cells." (PMID 30813264, 2019). "In light of the major roles that impaired Notch signaling plays in melanoma progression and induction of metastatic ability and in other diseases, we hypothesized that additional layers of regulation between Notch signaling and MITF signaling exist." (PMID 30699982, 2019). "Importantly, BRN2 may contribute to melanoma progression through regulation of MITF expression, repressing or activating the MITF promoter depending on cellular context." (PMID 30804224, 2019). "However, the expression of MITF negatively correlates with TFEB and TFE3 expression, raising the question whether MITF regulates a different set of lysosomal genes than the other factors in melanoma." (PMID 30705290, 2019). "In addition, single-cell expression analyses identified melanoma cells with a low MITF/AXL ratio in MITF-high bulk melanomas, which may be able to evade senescence and confer treatment resistance." (PMID 30651597, 2019). "MITF has been identified as a lineage survival oncogene amplified in malignant melanoma, CTLA-4 expression has been shown to be associated with a more favorable prognosis of patients with CM, and CD74 was identified as a useful prognostic marker associated with OS of patients in stage III melanoma." (PMID 31169496, 2019). "However, while overexpression of MITF in the MITF-low melanoma cells increases expression of several lysosomal and autophagosomal genes and results in increased autophagosome formation, MITF is not sufficient to drive a global increase in autophagy-mediated protein degradation." (PMID 30705290, 2019). "Notably, at the protein level MYC appeared to be decoupled from MITF in ∼15–20% of metastatic human melanoma samples (n = 18) and melanoma cell lines (n = 7) reflected by a low MITF/MYC expression ratio in whole cell lysates as demonstrated in immunoblot analyses." (PMID 30651597, 2019). "Mass spectroscopy and tandem affinity purification identified interaction of MITF with proteins directing DNA damage repair and replication, as well as components of the Polybromo and Brahma-related gene 1 (BRG1)-associated factor (PBAF) chromatin remodeling complex, in melanoma cells." (PMID 30871206, 2019). "Thus, MITF ensures the rapid resumption of transcription after completion of strand repair and maintains transcriptional output, which is indispensable for survival of the melanocytic lineage including melanoma in vitro and in vivo." (PMID 30651597, 2019). "Thus, different combinations of therapies should be effective in treating different phases of melanoma, such as the combination of targeted therapies with inhibitors of MITF expression during the initial treatment phase, but with inhibitors of WNT5A/AXL/NF-κB signaling during relapse." (PMID 29881716, 2018). "In addition, in mouse B16BL6 melanoma cells that were treated with isosakuranetin, a 4′-O-methylated flavonoid, a decreased phosphorylation of MITF and increased MITF stability has been observed through the suppression of ERK1/2 that subsequently stimulates melanogenesis." (PMID 30322121, 2018).
melanoma (continued). "Recently, two interesting studies which would at least partly explain the exclusive role of MITF in lowering invasiveness have implicated the expression of guanosine monophosphate reductase (GMPR), an enzyme of guanylate metabolism, in the regulation of invasiveness in melanoma cells." (PMID 29369499, 2018). "Furthermore, we found the inhibitory effects of the ethanol extracts of L. cuneata G. Don on wrinkle formation through up‐regulation of collagen synthesis in CCD986Sk human fibroblast cells and melanogenesis in B16F10 melanoma cells through downregulation of MITF, TRP1, and TRP2." (PMID 30065832, 2018). "Thus, modulation of MITF expression and activity can have diverse effects on melanoma cell biology." (PMID 29881716, 2018). "Interestingly, PGC-1α has been shown to regulate MITF expression in melanocytes, suggesting that a possible feed-forward mechanism might also occur in melanomas." (PMID 29629336, 2018). "However, the expression levels of MITF in various melanoma cell lines are highly variable and correlation to other receptor tyrosine kinases may be also implicated in acquired drug resistance." (PMID 29674683, 2018). "CDK4 alleles did not segregate with melanoma in a reference population, and lastly an association analysis showed that MITF could not be related to melanoma occurrence in the MeLiM model." (PMID 29963229, 2018). "A downregulation of the melanoma oncogene microphthalmia-associated transcription factor (Mitf) was observed, and most likely caused by the inhibition of Id2, a gene that regulated HLH transcription factors such as MITF and also reported to promote tumor cell migration and invasion." (PMID 30157785, 2018). "Another example is malignant melanoma, in which genes encoding the melanocyte lineage differentiation factors SRY-related HMG box 10 (SOX10), microphtalmia-associated transcription factor (MITF), and transcription factor AP2 alpha (TFAP2A) are commonly affected by promoter methylation." (PMID 29649096, 2018). "In addition to MITF, the AP-1 family of transcription factors (which includes c-Jun and c-Fos) is also a direct target of MAPK signaling, and it is highly associated with melanoma progression, proliferation, migration, apoptosis, and cell survival." (PMID 30166456, 2018). "In addition, expression of TRPM1 is a sensitive readout of MITF activity levels, and a minimal TRPM1 promoter, which has an MITF peak in melanoma cells and primary melanocytes, has activity in melanoma cells that is lost upon deletion of the MITF binding sites." (PMID 28249010, 2017). "As the studies of the major genomic aberrations in melanoma have been extensively reviewed elsewhere, this section will describe a number of the most common driver mutations seen in cutaneous melanoma [BRAF, NRAS, NF1, microphthalmia-associated transcription factor (MITF), and PTEN]." (PMID 29276510, 2017). "The 3’ UTR of microphthalmia-associated transcription factor (MITF) mRNA is also a binding site for CRD-BP and this interaction has been shown to be critical for protecting MITF transcript from degradation by miR-340, a mechanism believed to be important in melanocytes and melanoma." (PMID 28182633, 2017). "In addition, the effect of these alleles could be additive, especially when HERV-K proviruses are expressed due to general LTR activation (eg the reported induction by MITF in melanoma), instead of locus-specific expression." (PMID 28651004, 2017). "Moreover, we found that pre‐treated melanoma cells could produce this effect in other melanoma cell lines and that innate‐resistant high MITF‐expressing cell lines can also produce such a paracrine protective effect." (PMID 28606996, 2017).
melanoma (continued). "Indeed, they found in a zebrafish xenograft model that BRAF inhibitor‐pretreated melanoma cells, expressing elevated MITF levels, are not only more resistant to BRAF inhibition themselves, but also decrease the sensitivity to BRAF inhibition of untreated cells." (PMID 28694322, 2017). "MITF is the master regulator of the melanocyte differentiation program, therefore on one side it acts as a tumor suppressor, but on the other side it allows the retreat of melanoma cells into a “functional niche” in which they are protected from vemurafenib, hence it confers drug resistance." (PMID 28445987, 2017). "Indeed, in a panel of eight melanoma cell lines glucose levels regulated MITF mRNA levels." (PMID 28380427, 2017). "In addition, MITF is a potential therapeutic target for melanoma treatment." (PMID 28698805, 2017). "Indeed, depletion of FRA1 from melanoma cells leads to up‐regulation of MITF, but whether FRA1 directly acts as suppressor of MITF remains to be investigated." (PMID 28606996, 2017). "Interestingly, literature evidences carried out to date are not in contradiction with our results: Eccles el al. suggested the theory of “genetic switch”, as they described how PAX3-POU3F2 and MITF-miR-211 contribute independently to phenotypic fate of melanoma cells." (PMID 29156734, 2017). "In addition to this, we found SOX5 to be a novel regulator of MITF in human melanoma cells." (PMID 26927636, 2016). "Hence, well-balanced MITF homeostasis is important for the progression and spread of melanoma." (PMID 26927636, 2016). "Moreover, the gene expression reciprocity between NF-κB and MITF in melanoma and a transition between phenotypes MITF-Mhigh/NF-κBlow and MITF-Mlow/NF-κBhigh as a part of melanoma plasticity in response to therapies targeting the BRAF/MEK/ERK pathway have been proposed." (PMID 26824319, 2016). "We therefore examined the therapy phase before acquired resistance had developed and discovered the melanoma survival oncogene MITF as a driver of an early non-mutational and reversible drug-tolerance state, which is induced by PAX3-mediated upregulation of MITF." (PMID 26977879, 2016). "Moreover MITF controls the expression and activity of G1/S transition regulators such as p21, p27, and RB, all of which have been described to be affected by nelfinavir in melanoma cells." (PMID 26977879, 2016). "Therefore, it is difficult to use MITF itself for targeted therapy, but elucidating its complex regulation may lead to a promising melanoma-cell specific therapy." (PMID 26927636, 2016). "Moreover, inhibition of HDAC1 was reported as the mechanism of MITF downregulation in melanoma." (PMID 26824319, 2016). "In this study, we showed that Lebein blocks melanoma cell proliferation and induces a more differentiated phenotype with inhibition of extracellular signal-regulated kinase (ERK) phosphorylation and microphthalmia-associated transcription factor (MITF) overexpression." (PMID 27399772, 2016). "To determine whether the levels of ZEB1 and MITF were predictive of the patients’ response to MAPKi, we performed immunohistochemical staining for ZEB1, MITF but also TWIST1 on a cohort of 70 human BRAFV600 melanoma samples from patients whose response to the treatment was known." (PMID 27596438, 2016). "This discrepancy might indicate that MITF plays a complex role in melanoma drug response." (PMID 25890285, 2015). "Notably, exosome-dependent miR exchange between melanoma cells may influence MITF transcript level as well [for review 91]." (PMID 25433395, 2015). "Indeed, phospho‐ERK signals display significant heterogeneity within tumours, and considering phospho‐ERK levels when assessing BRN2 and MITF expression levels could help to shed more light on their regulation in melanoma." (PMID 25818589, 2015).
melanoma (continued). "The melanoma cell lines were classified as differentiated (n=12) or dedifferentiated (n=5) based on the expression levels of MITF (MITFhigh and MITFlow) and a set of bona fide pigmentation genes as measures of the transcriptional activity of MITF using hierarchical clustering." (PMID 26530832, 2015). "However, in melanocytes or BRAFWT B16 melanoma cells, MITF co‐immunoprecipitates with p300 in a S73 phosphorylation‐independent manner, possibly because in these cells, the MAPK pathway is not significantly activated and the interaction is regulated in a different manner." (PMID 25818589, 2015). "Together, the expression of a MITF‐induced ‘antiproliferative’ factor in the context of cAMP signalling might depend on the concomitant activation of additional signals, a scenario that would reconcile high MITF expression levels with melanoma cell proliferation." (PMID 25818589, 2015). "Moreover, a reduction of MITF activity sensitizes melanoma cells to chemotherapeutic agents." (PMID 26322273, 2015). "Moreover, since HINT1 expression is lost in primary melanomas, it may support a role of MITF in melanomagenesis." (PMID 25433395, 2015). "MITF (Microphthalmia-associated transcription factor) belongs to the Myc superfamily of basic helix-loop-helix leucine zipper transcription factors and is a downstream target of WNT/β-catenin signaling that has been reported to induce proliferative effects in melanocytes and melanoma cells." (PMID 26393652, 2015). "Moreover, as BPTF is essential in 1205Lu cells, it may have both MITF-dependent and independent functions in melanoma." (PMID 26440048, 2015). "Additionally, DNA methylation levels at the promoter regions of BAP1, MITF, and PALB2 genes were statistically associated with the number of melanomas presented by the individual and a hypermethylation of POT1 promoter was associated with Breslow thickness of the tumors." (PMID 26106605, 2015). "Hence, this difference in the kinetics demonstrates how MITF loss overrides intrinsic negative feedbacks of inflammatory signalling pathways and progressively drives the establishment of an inflammatory melanoma cell state." (PMID 26530832, 2015). "Oncogenic BRAF (but not wildtype BRAF), which is mutated in up to 50% of melanomas, also regulates MITF via simultaneously stimulating MITF activation through ERK phosphorylation, which leads to its subsequent degradation, and by inducing transcription of MITF via BRN2 upregulation." (PMID 25755924, 2015). "Thus, the role of ZEB1 in the context of MITF expression in melanoma needs to be elucidated." (PMID 25433395, 2015). "However, the molecular mechanisms remain unclear how MITFlow melanoma cell lines become independent from the MITF-driven proliferative programme, assuming that they underwent a phenotypic transition and originated from a MITFhigh cell state." (PMID 26530832, 2015). "Thus, in melanoma cells, p21CIP1 as MITF target might play another role than inhibiting the cell cycle." (PMID 25818589, 2015). "Thus, DKK1 and MITF might be considered as important regulators of microenvironment-driven alterations of melanoma phenotype." (PMID 24733089, 2014). "MITF expression was significantly inhibited by 0.1 μM maytansine, toyocamycin and colchicine, whereas its expression was significantly higher in melanoma cells treated with 0.1 μM streptonigrin and 0.4 μM geldanamycin analog for 24 h." (PMID 24595456, 2014). "However, SNAI2 was recently reported to be co-expressed with MITF during melanoma progression." (PMID 25593989, 2014).